ANKHD1-EIF4EBP3 (ANKHD1-EIF4EBP3 readthrough)
Synonyms: MASK-BP3; MASK-BP3ARF
Gene: Protein-coding gene on chromosome 5 (140,401,908 to 140,549,569, forward strand). Ensembl gene ENSG00000254996.
Genetic constraint (gnomAD): Loss-of-function variants: 37 observed, 238.15 expected, observed/expected ratio (o/e) 0.16, 90% interval 0.12 to 0.2. The upper end of that interval is the gene's LOEUF score, 0.2, which puts it in group 1 of 6, group 1 being the genes least tolerant of losing a copy. Missense variants: 2,351 observed, 3,237.7 expected, observed/expected ratio (o/e) 0.73, 90% interval 0.7 to 0.75. Synonymous variants: 1,118 observed, 1,191.9 expected, observed/expected ratio (o/e) 0.94, 90% interval 0.89 to 0.99.